CFAP96 (cilia and flagella associated protein 96)
Synonyms: C4orf47; LOC441054
Tractability: PROTAC: ubiquitination databases record sites on it.
Gene: Protein-coding gene on chromosome 4 (185,426,014 to 185,449,828, forward strand). Ensembl gene ENSG00000205129.
Subcellular location: Cytoplasm, cytoskeleton, microtubule organizing center, centrosome
Subcellular location (Human Protein Atlas): End piece; Principal piece
Gene Ontology:
Cellular component: 9+0 non-motile cilium; centrosome; cytoplasmic microtubule
Genetic constraint (gnomAD): Loss-of-function variants: 19 observed, 20.46 expected, observed/expected ratio (o/e) 0.93, 90% interval 0.65 to 1.36. The upper end of that interval is the gene's LOEUF score, 1.36, which puts it in group 5 of 6, group 1 being the genes least tolerant of losing a copy. Missense variants: 217 observed, 244.4 expected, observed/expected ratio (o/e) 0.89, 90% interval 0.79 to 0.99. Synonymous variants: 81 observed, 81.04 expected, observed/expected ratio (o/e) 1, 90% interval 0.83 to 1.2.
Homologues: Orthologues: chimpanzee CFAP96 (98% identical), macaque CFAP96 (94% identical), pig CFAP96 (85% identical), rabbit CFAP96 (84% identical), dog CFAP96 (83% identical), guinea pig CFAP96 (77% identical), rat Cfap96 (77% identical), mouse Cfap96 (77% identical), tropical clawed frog cfap96 (58% identical), zebrafish cfap96 (55% identical).
Diseases named in the same sentence as CFAP96 in open-access papers:
CFAP96 is named in the same sentence as 13 diseases in open-access papers, as found by Europe PMC text mining. Sharing a sentence is not in itself a finding about the gene and the disease.
CFAP96 shares sentences with these, for which no sentence is quoted: cancer (2 papers); breast carcinoma (1); colorectal cancer (1); glioma (1); kidney cancer (1); liver cancer (1); lung carcinoma (1); melanoma (1); pancreatic cancer (1); prostate carcinoma (1); testicular cancer (1); thyroid cancer (1); uterine cancer (1).